ULK1 (unc-51 like autophagy activating kinase 1)
Diseases named in the same sentence as ULK1 in open-access papers (continued):
Sharing a sentence is not in itself a finding about the gene and the disease.
esophageal squamous cell carcinoma (15 papers, 2013 to 2025). Esophageal squamous cell carcinoma (ESCC) is a type of esophageal carcinoma (EC) that can affect any part of the esophagus, but is usually located in the upper or middle third. "It efficiently suppressed the proliferation of both imatinib-sensitive and -resistant CML cells via the mechanistic target of rapamycin (mTOR)-Unc-51-like kinase 1 (Ulk1) pathway and can sensitize esophageal squamous cell carcinoma to radiotherapy." (PMID 41425251, 2025). "RPTOR/ULK1/autophagy axis influence esophageal squamous cell carcinoma tumorigenesis." (PMID 38240686, 2024). "Ulk1, which plays an essential role in autophagosome formation through activation or regulation of the AMP activated protein kinase and mTOR, is overexpressed in esophagus squamous cell carcinoma." (PMID 23593401, 2013). "Given that CLDN1 is mostly found in the nucleus of esophageal squamous cell carcinoma (ESCC) and has been shown to be abnormally elevated, CLDN1 promotes ESCC growth and metastasis by upregulating the expression of ULK1 via the AMPK/STAT1 signaling pathway." (PMID 36620607, 2022).
melanoma (15 papers, 2015 to 2025). A malignant, usually aggressive tumor composed of atypical, neoplastic melanocytes. "ULK1 is involved in the invasiveness of BRAFi-resistant melanoma cells, and it has also been associated with the development of resistance to ICIs in melanoma." (PMID 39970778, 2025). "In this respect, the melanoma cell phenotype during therapeutic resistance can be more complex because of the crucial role of other copper-regulated proteins, as exemplified by ULK1." (PMID 39970778, 2025). "Previously, we have shown LncRNA PURPL directly interacts with ULK1 to promote mTOR-mediated phosphorylation of ULK1 at Ser757 to repress autophagic cell death and promote melanoma cell survival." (PMID 40651979, 2025). "Depletion of PURPL leads to AMPK-mediated phosphorylation of ULK1 at Ser555 and Ser317, which promotes autophagic cell death and thereby inhibits melanoma development." (PMID 40651979, 2025). "The inhibition of ULK1 substantially reduces IFNγ-induced PD-L1 and PD-L2 expression in melanoma cells." (PMID 38067169, 2023). "Accordingly, the combination treatment of a ULK1 inhibitor with anti-PD1 increases tumor regression in a subcutaneous melanoma implant model through a reduction in PD-L1/L2 levels and enhances the infiltrating efficacy of anti-tumor immune cells." (PMID 38067169, 2023). "Upregulated ULK1 in melanoma cells is positively correlated with the IFNγ-induced expression of immunosuppressive genes, such as PD-L1 and PD-L2." (PMID 38067169, 2023). "Collectively, the in vivo experiments indicated that PURPL functions in repressing autophagic cell death to promote melanoma growth by differentially modulating ULK1 phosphorylations." (PMID 34759263, 2021). "Mechanistic study showed that PURPL physically interacts with ULK1 and differentially regulates its phosphorylation to suppress autophagic cell death to maintain the survivability of melanoma cells." (PMID 34759263, 2021). "And, another study has recently reported that the miR-290–295 cluster suppresses autophagic cell death by targeting ULK1 in melanoma cells." (PMID 26183158, 2015). "Mechanistically, high levels of ULK1 are associated with the interferon-gamma (IFN-γ)-induced immunosuppressive response of melanoma cells, indicating that a copper chelation strategy can also be considered in melanoma patients treated with ICIs." (PMID 39970778, 2025). "PURPL physically interacts with ULK1 and differentially regulates its phosphorylation by promoting the association with mTOR and departure from AMPK to suppress autophagic cell death for maintaining the survivability of melanoma cells." (PMID 36918934, 2023). "Our findings highlight a novel oncogenic role of PURPL to suppress autophagic cell death mediated by regulating differential ULK1 phosphorylation in melanoma, which may provide novel intervention targets for melanoma therapy." (PMID 34759263, 2021). "Our results identify PURPL as a key regulator to modulate the activity of autophagy initiation factor ULK1 to repress autophagic cell death in melanoma and may represent a potential intervention target for melanoma therapy." (PMID 34759263, 2021). "Thus, we hypothesized that PURPL intervenes in autophagy to modulate melanoma progression by directly interacting with ULK1 and mTOR." (PMID 34759263, 2021). "ILK knockdown decreased ULK1 phosphorylation at S757, which probably enabled its interaction with AMPK in the melanoma cell line WM793." (PMID 33916175, 2021). "In melanoma cells, miR-290-295 cluster suppressed autophagic cell death in response to glucose starvation through the down-regulation of ATG7 and ULK1." (PMID 26878873, 2016).
melanoma (continued). "Wengrod and colleges have shown that mTORC1 regulation of autophagy in melanoma needs eIF2α phosphorylation in a pathway independent of ULK1/2." (PMID 33916175, 2021). "Whether ULK1 acquires pro-death properties and mediates ROS-induced cell death in non-pigmented melanoma cells remains to be investigated." (PMID 27896217, 2016).
acute myeloid leukemia (14 papers, 2015 to 2025). Acute myeloid leukemia (AML) is a group of neoplasms arising from precursor cells committed to the myeloid cell-line differentiation. "Of note, the association of PDK1 with unc-51-like autophagy-activating kinase 1 (ULK1) was shown to regulate autophagy in acute myeloid leukemia (AML) cell lines." (PMID 30250843, 2018). "For example, SBI-0206965, as a small molecule inhibitor of ULK1, has been found to enhance daunorubicin sensitivity in acute myeloid leukemia." (PMID 33344463, 2020). "IGF2BP2 and IGF2BP3 augmented the stability of DDX21 mRNA in an m6A-dependent manner, followed by recruitment of transcription factor YBX1 by DDX21 on ULK1 gene promoter and elevated transcription of ULK1, which facilitates progression of acute myeloid leukemia." (PMID 39866844, 2025). "Moreover, miR-106a targets the important autophagy gene ULK1 in acute myeloid leukemia cells." (PMID 33505399, 2020). "For example, miR-106a directly down regulates ULK1 mRNA levels in acute myeloid leukemia (AML) cells, and can also target other members of the ULK1 complex such as mAtg13 and FIP200." (PMID 25593195, 2015). "Mitophagy is AMPK-mediated through phosphorylation of ULK1 (unc-51 like autophagy activating kinase 1) protein at Ser555 in human MSC, human acute myeloid leukemia stem cells and mouse skeletal muscle." (PMID 33070285, 2020). "Autophagy-related proteins such as ULK1, ATG3, ATG5, ATG13, and ATG14 were markedly expressed in various acute myeloid leukemias when comparing the microarray-based expression profiling of distinct ATG proteins from human AML samples with the human normal hematopoiesis." (PMID 37180758, 2023). "In acute myeloid leukemia (AML), DDX21 recruits YBX1 to cooperatively trigger ULK1 expression and promote AML progression." (PMID 40301349, 2025). "SBI0206965 is a highly selective inhibitor of ULK1 kinase and it has been reported to sensitize NSCLC cells and acute myeloid leukemia (AML) cells to cisplatin- and daunorubicin-based chemotherapy, respectively, by decreasing cancer cell viability." (PMID 33718194, 2021).
ovarian carcinoma (14 papers, 2015 to 2026). A malignant neoplasm originating from the surface ovarian epithelium. "Our findings demonstrate that ULK1 inhibition via MRT68921 consistently reduces cell viability across multiple ovarian cancer models, supporting ULK1 as a promising therapeutic target." (PMID 41595226, 2026). "SH3PXD2A forms a complex with ULK1 and MTOR, and the ULK1-SH3PXD2a-MMP14 axis upregulates the aggressiveness of ovarian cancer." (PMID 38903532, 2024). "In ovarian cancer cells, inhibiting autophagy regulator—ULK1, can decrease the autophagy, and repress viability and suspension growth of high-grade serous ovarian cancer (HGSOC) cells." (PMID 36805591, 2023). "Chemoresistance in ovarian cancer may be enhanced by ULK1-mediated autophagy." (PMID 36805591, 2023). "In ovarian cancer, elimination of autophagy mediated by DIRAS3 and ULK1 via the lncRNA RNF157-AS1 reduced the resistance of ovarian cancer cell resistance to DDP." (PMID 38933333, 2024). "Under the same conditions, autophagosome proteins such as BECN1, p-ULK1, ATG5, and LC3B were induced by β-sitosterol in the examined ovarian cancer cells." (PMID 34679718, 2021). "We confirmed these results, noting significant downregulation of p-AKT, p-ERK, p-mTOR, p-ULK1, p-P70S6K in A2780 ovarian cancer cells following both amino acid deprivation as well as complete serum starvation (HBSS supplemented with 3% glucose) at 2–4 h." (PMID 31052266, 2019).
Sepsis (13 papers, 2017 to 2026). Sepsis is defined as life-threatening organ dysfunction caused by a dysregulated host response to infection. "However, evidence on the association of ULK1 with sepsis is scarce." (PMID 37861563, 2023). "NAT10 mediated ac4C modification of ULK1 also regulates neutrophil pyroptosis in sepsis by activating STING pathway." (PMID 38689229, 2024). "ULK1 is an important element of the autophagy process and was identified to be involved in sepsis via various mechanisms." (PMID 37861563, 2023). "Of note, it was recently reported that NAT10 regulates pyroptosis in sepsis through the acetylation of ULK1 RNA in the STING pathway via the ULK1-STING-NLRP3 axis." (PMID 37237981, 2023). "In other words, the downregulation of NAT10 in neutrophils contribute to the progress of sepsis by exacerbating pyroptosis in neutrophils via promoting the ULK1-STING-NLRP3 axis." (PMID 36068299, 2022). "The enzyme N-acetyltransferase NAT10 is a negative regulator of neutrophil pyroptosis and its downregulation contributes to the progress of sepsis by exacerbating pyroptosis via the ULK1-STING-NLRP3 pathway." (PMID 36068299, 2022). "Clinically, the decreased expression of ULK1 was also observed in BALF neutrophils of sepsis patients, which was positively correlated with the APACHE II score indicating the clinical severity." (PMID 36068299, 2022). "We speculate that activation of DRAM1 may upregulate autophagy to counter bacterial infection, leading to expansion of C10_ULK1 cells in sepsis." (PMID 37919720, 2023). "Therefore, our data indicate that the therapeutic effect of neutrophil-specific NAT10 over-expression on sepsis by inhibiting pyroptosis is mediated by the ULK1-STING-NLRP3 axis." (PMID 36068299, 2022). "Finally, to determine the role of ULK1-mediated STING-NLRP3 axis in NAT10-dependent alleviation of sepsis, STING inhibitor C-176 was administered to wild type sham or CLP-induced septic mice." (PMID 36068299, 2022). "Both gastrocnemius and diaphragm muscles displayed a transitory increase (day 1) in the transcript level of autophagy-related genes (Ulk1, LC3b), together with an increase in LC3b-II-to-LC3b-I ratio, suggesting that autophagosome formation would be increased in response sepsis." (PMID 28883493, 2017). "The study explored whether (i) upregulating 14-3-3γ via Cap pretreatment contributed to autophagy via the AMPK-mTOR/ULK1 pathway against LPS-induced sepsis to myocardial injury (ii) Cap protected cardiomyocytes from LPS-induced inflammation, excessive oxidative stress, and mitochondrial dysfunction." (PMID 33986684, 2021). "In sepsis, reduced NAT10 expression lowers the ac4C modification level of ULK1 mRNA, leading to decreased ULK1 mRNA stability and increased degradation." (PMID 41513612, 2026). "For example, the outgoing signaling of C1_CD36, C3_B, C9_STOM, and C10_ULK1 cells was dominated by “pattern 1,” which included RESISTIN and VISFATIN in sepsis." (PMID 37919720, 2023). "Collectively, our findings disclose that NAT10 is a negative regulator of neutrophil pyroptosis and its downregulation contributes to the progress of sepsis by exacerbating pyroptosis via the ULK1-STING-NLRP3 axis, therefore revealing a potential therapeutic target for sepsis." (PMID 36068299, 2022). "The study found that over-expression of miR-335-5p induced autophagy by activating the AMPK/ULK1 (AMP-activated protein kinase/unc-51 like autophagy activating kinase 1) signaling pathway and attenuating the inflammatory response in a mouse model of sepsis." (PMID 31507440, 2019). "Although Beclin1, Atg7, and Atg12 in the Sepsis group were all slightly higher than the SFP group (p < 0.05), Unc-51-like autophagy activating kinase (Ulk1), Atg5, Atg8l, and Lamp2 were not different." (PMID 37106730, 2023).
Hepatic steatosis (12 papers, 2016 to 2026). Steatosis is a term used to denote lipid accumulation within hepatocytes. "Second, gemigliptin treatment alleviated hepatic steatosis in association with increasing ULK1 expression and autophagy." (PMID 37739179, 2023). "In both patients and mice with fatty liver, there is decreased expression of Ulk1, an autophagy-related gene." (PMID 36864020, 2023). "In the same context, suppression of Mir214-3p expression increased autophagy by increasing the expression of ULK1, thereby improving fatty liver disease." (PMID 37739179, 2023). "In conclusion, our study found that gemigliptin effectively ameliorates hepatic steatosis, inflammation, and fibrosis in an MCD diet–induced NASH model mice by enhancing autophagy through an increase in ULK1 expression." (PMID 37739179, 2023). "Herein, we show that ULK1, a serine/threonine kinase and core autophagy protein, is significantly repressed in human MASH livers, and that hepatocyte-specific loss of ULK1 promotes, unexpectedly, hepatic steatosis and progression to liver fibrosis, without affecting basal autophagy flux." (PMID 41926189, 2026). "Herein, MG increased ATG5-12, ATG7, Beclin1, ULK1, and LC3-II/I ratio and decreased p62/SQSTM1 and p-mTOR in the liver of Tylo-injected rats and PA-stimulated HepG2 cells, suggesting that MG might promote the formation of autophagic flux to alleviate hepatic steatosis." (PMID 32992548, 2020).
leukemia (12 papers, 2020 to 2024). A malignant (clonal) hematologic disorder, involving hematopoietic stem cells and characterized by the presence of primitive or atypical myeloid or lymphoid cells in the bone marrow and the blood. "In co-immunoprecipitation assays using two JAK2V617F-expressing leukemia cell lines, we found ULK1 associated with PKCδ, both before and after IFNα-treatment." (PMID 35365653, 2022). "A growing number of studies have found that ULK1 can influence leukemia development by regulating autophagy in various types of leukemia cells." (PMID 38887520, 2024). "The proteins mainly play a role in the two processes of autophagy initiation and mature autophagosome formation in leukemia, mainly ULK1 complex, Beclin-1 protein, and ATG-related proteins." (PMID 38887520, 2024). "ULK1 inhibitors effectively induce mitochondria-mediated, caspase-dependent apoptosis in FLT3-ITD-mutated leukemia cell lines and primary leukemia cells." (PMID 38307903, 2024). "The ULK1 protein and Beclin-1 protein play a key role in the autophagy process of leukemia." (PMID 38887520, 2024). "Therefore, caspase-3 modulates ULK1-mediated macroautophagy activation to limit AML1-ETO9a-driven leukemia." (PMID 35526025, 2022). "In this study, we evaluated the effects of ULK1 inhibition on leukemia cell death in FLT3-ITD AML." (PMID 32393312, 2020). "Atg13 and FIP200 are reduced in TRPM2-depleted leukemia cells, and this may contribute to reduced ULK1 stability." (PMID 32312983, 2020). "ULK1 inhibition also induced cell death, albeit to a lesser degree, in FLT3-WT leukemia cells, necessitating a clarification of whether the apoptosis-inducing effects of ULK1 inhibition were primarily due to ULK1 inhibition or off-target effects thereof." (PMID 32393312, 2020). "We demonstrated here for the first time that two ULK1 inhibitors, MRT 68921 and SBI-0206965, induced caspase-dependent apoptosis preferentially in FLT3-ITD-mutated leukemia cell lines and primary leukemic blasts obtained from FLT3-ITD AML patients, while sparing normal CD34 (+) cells." (PMID 32393312, 2020). "In another study, knockdown of ULK1 downregulated the MCL1 gene; damaging leukemia cells by impairing mitochondrial function and downregulating CD44-xCT, resulting in ROS mitigation of DNA damage and promotion of apoptosis." (PMID 38887520, 2024). "The ULK1 promoter has several putative CREB sites, and CREB is downregulated in TRPM2-depleted leukemia cells." (PMID 32312983, 2020). "For example, punicalagin exerts the cytotoxic effect by suppressing proliferation and promoting apoptosis and autophagy by activating the caspase cascade, altering Bax and Bcl-2, and regulating autophagy via mTOR/ULK1 signaling in human NB4 and MOLT-4 leukemia cell lines." (PMID 35745713, 2022). "Moreover, when AML-bearing mice were treated with MRT-68921, with a lower IC50 against its molecular target, ULK-1, than SBI-0206965, both total WBCs and leukemia cells were efficiently reduced in the PB with an improved survival rate." (PMID 33771977, 2021). "The interaction between ULK1 and caspase-3 was demonstrated in AML1/ETO leukemia cells." (PMID 32393312, 2020). "Particularly, the action spectrum of these ULK1 inhibitors has not been fully evaluated in cancer cells, including leukemia blasts, which are considered to have abnormal autophagy regulatory mechanism in a context-dependent manner." (PMID 32393312, 2020). "In addition, leukemia stem cells (LSCs) showing resistance to bromodomain and extraterminal domain inhibitors exhibited upregulation of BECN1/Beclin-1 and increased autophagy via activation of the AMPK (p-Thr172)/ULK1 (p-Ser555) pathway." (PMID 35526025, 2022).
leukemia (continued). "This constitutive interaction between PKCδ and ULK1, however, was not JAK2V617F-dependent, as it was also detected in JAK2V617F-negative leukemia lines." (PMID 35365653, 2022).
prostate carcinoma (11 papers, 2016 to 2024). A carcinoma that arises from epithelial cells of the prostate gland. "As opposed to that observed for ATG5, high tumour protein expression of ULK1 has been found to significantly associate with biochemical recurrence following radical prostatectomy of prostate cancer patients." (PMID 38910881, 2024). "GZ17-6.02 was significantly better at killing MM cells than prostate cancer cells, and in both tumor types, knock down of ULK1, Beclin1 or ATG5 reduced both autophagosome formation and tumor cell killing." (PMID 38441437, 2024). "In prostate cancer cells, autophagy is increased due to ULK1/2 overexpression, so, these cells are resistant to different drug treatments, but, when mir-26a is overexpressed, these cells get sensitized." (PMID 34123772, 2021).